AQP1 (aquaporin 1 (Colton blood group))
Diseases named in the same sentence as AQP1 in open-access papers (continued):
Sharing a sentence is not in itself a finding about the gene and the disease.
tumor (189 papers, 2002 to 2025). "AQP1 has been linked to tumor development due to its ability to alter the expression of crucial cell cycle proteins, which appears to be associated with an increase in cell proliferation." (PMID 39857629, 2024). "The exact mechanisms underlying the effect of AQP1 on tumor proliferation remain incompletely understood." (PMID 38334883, 2024). "Due to its association with tumour invasiveness and the fact that it is consistently overexpressed from the earliest to the latter stages of colorectal carcinogenesis, AQP1 is now considered a poor predictive biomarker of patient survival." (PMID 38336645, 2024). "Given that BM-MSCs have been shown to differentiate into cancer-associated fibroblasts that further promote tumor growth and metastasis, AQP1 appears to play a significant role in the complex interactions between the tumor microenvironment and tumor cells." (PMID 37762642, 2023). "High cytoplasmic expression of AQP1 was found to be positively associated with pathological tumor size (pT)." (PMID 36803413, 2023). "Potential downstream effectors in the signaling pathways involved in AQP1-mediated tumor progression include β-linked protein, Lin-7, FAK, MMP2, MMP9, and histone proteinase B." (PMID 37334171, 2023). "Initially identified as a water channel protein, AQP1 has also been implicated in cell migration and tumor formation." (PMID 38057925, 2023). "The expression of AQP1 in certain tumor types is associated with increased angiogenesis, invasion, metastasis, and proliferation." (PMID 36532729, 2022). "In TNBC, AQP1 expression was associated with poor survival, where high AQP1 expression was associated with high tumor grade and hormone receptor negativity." (PMID 36212456, 2022). "We conclude that AQP1 expression is linked to a hypoxic profile as well as it is clearly a driving factor in tumor cell migration." (PMID 33467498, 2021). "A possible functional importance of AQP1 in tumor biology has been suggested regarding tumor-associated edema, facilitated tumor angiogenesis and endothelial cell migration, tumor cell extravasation and metastasis." (PMID 33644043, 2021). "AQP1 expression and its migratory ability are strongly linked to a hypoxic and undifferentiated profile of the tumor cell even under seemingly normoxic conditions." (PMID 33467498, 2021). "Especially AQP1, the first water channel described, is expressed in several tumor tissue and has been linked with the promotion of migration." (PMID 33467498, 2021). "In TNBC, Aquaporin 1 (AQP1), a water-transporting transmembrane protein, is aberrantly enriched in cytoplasm and causes tumor cell death evasion." (PMID 33980862, 2021). "Bac I and II are proven modulators of aquaporin 1 (AQP1), a transmembrane protein with water and ion channel functions, which has been implicated in tumour proliferation, migration, and angiogenesis." (PMID 34066415, 2021). "AQP1 analysis has been investigated in several neoplastic tissues, in which a significant association between its expression, tumor phenotype and survival outcomes has been documented." (PMID 33807998, 2021). "For instance, miR320 is downregulated in plasma and tumor tissues of BC patients, and its target gene AQP1 is highly expressed, both of which are associated with poor prognosis." (PMID 32903818, 2020). "Concrete evidence shows that, after subcutaneous or intracranial tumor cell implantation, tumor growth is significantly inhibited in AQP1-deficient mice with reduced tumor vasculature and extensive necrosis." (PMID 32903818, 2020). "AQP1 is strongly associated with many important tumor signaling pathways that promote cell proliferation and contribute to carcinogenesis, such as NF-κB, Notch, PI3K/Akt, and p38-MAPK pathways." (PMID 32373535, 2020).
tumor (continued). "So far, studies have shown that membrane AQP1 expression is associated with triple-negativity, expression of cytokeratin 14 and smooth muscle actin, higher tumor grade, medullary-like histology and poor clinical prognosis." (PMID 30678106, 2019). "One of the proposed mechanisms underlying AQP1-mediated cancer development and growth is enhanced tumour angiogenesis." (PMID 31013775, 2019). "In detail, according to two recent studies on large series, high levels of immunohistochemically expressed AQP1, in over 50% of tumor cells, seemed to be linked with improved overall survival (OS) in these patients." (PMID 29495596, 2018). "We first analysed the expression level of HIF‐1α, which resulted up‐regulated in AQP1 siRNA‐treated tumour, as expected, being AQP1 silencing associated with reduced tumour angiogenesis." (PMID 29044946, 2018). "In tumor disease, for example, there is evidence that up-regulation of AQP1 expression is linked to hypoxia." (PMID 28762291, 2017). "More recently, association of AQP1 with tumour microenvironment-driven tumour growth has been suggested." (PMID 28146084, 2017). "This loss of AQP1 in long-term tumor cell cultures and cell lines is likely a result of culture condition." (PMID 26812884, 2016). "Among the genes exhibiting altered expression levels, aqp1, map3k5, and fgf18 are highly expressed in tumor-associated blood vessels in several human tumors." (PMID 23929008, 2014). "AQP1 is up-regulated in choroids plexus tumours, which are associated with increased CSF production, against supporting a role for this isoform in CSF secretion." (PMID 21119880, 2010). "Moreover, Yang and colleagues reported that the epithelial ovarian tumours and AQP1 expression was associated with intra-tumoral microvascular density and the phase of the tumour." (PMID 38336645, 2024). "Also, AQP1 was a key player in tumor angiogenesis, where AQP1 depletion caused abnormal tumor microvasculature." (PMID 36212456, 2022). "The water channel aquaporin 1 (AQP1) has been implicated in tumor progression and metastasis." (PMID 33644043, 2021). "Moreover, AQP1/3/4/5 expression was strongly associated with tumor-infiltrating lymphocytes (TILs) in LUAD." (PMID 34708074, 2021). "All these findings suggest that miR-3194-3p and AQP1 are involved in carcinogenesis and may be associated with the tumor malignancy of BC." (PMID 32903818, 2020). "The analysis was later focused on testing whether the reduction in AQP1‐dependent vascularization caused hypoxia and tumour cell apoptosis." (PMID 29044946, 2018). "AQP1 has been implicated in tumour progression in murine models and may thus serve as a potential target for small molecule inhibitors to treat cancer in subgroups expressing AQP1." (PMID 26912239, 2016). "Because AQP1 is expressed in normal mesothelium, and the level of differentiation in MM is thought to decrease from epithelioid to biphasic to sarcomatoid subtypes, it is conceivable that loss of AQP1 expression is an indication of further tumour de-differentiation." (PMID 27376267, 2016). "Therefore, the abnormal investment of some tumor-associated capillaries with contractile pericytes (immature; AQP1+CD34+αSMA+) may indicate a dysfunctional phenotype." (PMID 38361951, 2024). "In the cited study, the authors compared the expressions of all aquaporin encoding genes (AQP1/2/3/4/5/6/7/8/9/10/11) in 533 tumor cases with 72 normal cases, using the uniform fold-change threshold of 1.50× and p-value < 0.01, to decide whether a gene was significantly regulated." (PMID 38132440, 2023). "In addition, AQP1 upregulation is associated with angiogenesis and tumor-associated edema formation and AQP4 redistribution might be functional in the reabsorption of excess cerebral fluid during vasogenic edema." (PMID 34712604, 2021). "In addition, tumor microvessel proliferation is impaired in AQP1‐deficient mice." (PMID 32253832, 2020).
tumor (continued). "After comprehensive and robust multidimensional validation, incorporating differential expression analyses and survival assessments, three key tumor stemness-associated genes—REN, AQP1, and SFRP2—were carefully compared." (PMID 40534868, 2025). "On one hand, AQP1 has been suggested to act as a tumor suppressor inhibiting the growth of HNSCC 64,65." (PMID 40386053, 2025). "Since AQP1 is overexpressed in tumor endothelial cells, this protein is crucial for angiogenesis, endothelial cell migration and tumor growth, enhancing tumor infiltration and spread." (PMID 39941100, 2025). "PRDX2, PKD2 (polycystin-2), and AQP1 were overexpressed in tumor tissues, whereas SOD3 and KLF2 were downregulated." (PMID 41140697, 2025). "In tumor-bearing AQP1-null mice, there is reduced tumor angiogenesis and AQP1-deficient ECs display reduced migration in an in vitro wound-healing assay." (PMID 39977018, 2025). "In the context of cancer, the expression of specific aquaporins, such as AQP1 and AQP3, has been associated with enhanced migration and invasion of tumor cells." (PMID 40283503, 2025). "The expression of AQP1 was also significantly negatively correlated with tumor grade and specific survival in ccRCC." (PMID 38334883, 2024). "After 6 days of therapy, tumours treated with AQP1 siRNA exhibited a 75% decrease in volume in comparison to controls which were related to a substantial drop in expression of the endothelium marker factor VIII." (PMID 38336645, 2024). "Levels of COX-2, AQP1, and G17 positively correlated with the tumor, node and metastasis (TNM) staging, infiltration depth, and the lymph node metastases, and negatively correlated with the degree of differentiation (P<0.05)." (PMID 39634909, 2024). "This "osmotic engine model" perfectly explains how membrane AQP1 regulates tumor migration and angiogenesis." (PMID 38307919, 2024). "AQP1 is a water channel that is expressed in a variety of cell types and tissues, including red blood cells, endothelium, renal tubules, tumor cells, and sweat glands." (PMID 39175041, 2024). "Tumor cells expressing a high level of AQP1 exhibit higher proliferation and migration rates, resulting in more extensive tumors and more frequent lung metastases in vivo." (PMID 38307919, 2024). "Recent studies have expanded Aqp1 beyond our initial proof-of-concept by demonstrating that Aqp1 can be used to track tumor-specific gene expression, trace neural connectivity, and generate brain-wide maps of astrocyte populations in mice." (PMID 38649904, 2024). "We tested Aqp1 for its ability to sufficiently enhance water diffusivity in several different cell lines of neuronal, macrophage, pancreatic, T-lymphocyte, and tumor origin from both mouse and human lineages, confirming its broad utility as an MRI reporter." (PMID 38649904, 2024). "In our preliminary study, we conducted bioinformatics analysis and identified AQP1 as a potential key tumor suppressor gene involved in the occurrence and development of WT." (PMID 38334883, 2024). "Histological samples of tumor and normal brain tissues from the Human Protein Atlas database show the distribution of AQP1 and AQP4 proteins." (PMID 38476871, 2024). "AQP1 is crucial for regulating water transport by the tumor cells and affects tumor vascular formation and migration." (PMID 38791252, 2024). "In osteosarcoma and hepatocellular carcinoma, inhibition of AQP1 hampered tumor cell migration and invasion." (PMID 36803413, 2023). "The high AQP1 expression was strongly associated with worse 5-year PFS and OS, which supports that high AQP1 expression can promote tumor invasion and reduce patient survival." (PMID 37334171, 2023). "The AQP1, 3 and 5 expression and clinicopathologic factors, including age, gender, primary tumor site, histological grading, TNM-stage and treatment strategy, were submitted into univariate and multivariate COX regression analysis." (PMID 37334171, 2023).
tumor (continued). "Compared with control group, the tumor volume from AQP1 overexpression mice group was remarkably increased." (PMID 36803413, 2023). "AQP subtypes, such as AQP1, AQP3, and AQP5, have been implicated in various aspects of carcinogenesis, tumor progression, and invasion." (PMID 38057925, 2023). "One proposed mechanism by which AQP1 facilitates tumor cell migration involves osmotic water flow across the plasma membrane." (PMID 37762642, 2023). "The role of AQP1 in cancer progression extends beyond its well-known function in water transport, particularly implicating it in the critical processes of tumor cell migration and invasion." (PMID 37762642, 2023). "Studies conducted on AQP1 knockout (KO) mice have demonstrated impaired tumor growth, cell migration, and angiogenesis." (PMID 38057925, 2023). "AQP1 appears to have a multifaceted role in cancer progression, impacting both tumor cells and the surrounding microenvironment." (PMID 37762642, 2023). "Different levels of AQP1 expression has been shown to correlate with tumor stage in cancer patients." (PMID 36672280, 2023). "Variability in the effectiveness of AqB011 between tumor tissues was investigated by comparing levels of AQP1 protein expression and the inhibitory effect of AqB011 within each sample." (PMID 37760476, 2023). "The anti-invasive potency of AqB011 treatment for EC tumor tissues showed a positive linear correlation with AQP1 expression levels." (PMID 37760476, 2023). "Although the percentage of these patients with neoplasms in the cohort was considerable (14%), the small number prohibits definite conclusions regarding the frequency of neoplasms in AQP1-Abpos patients." (PMID 37629163, 2023). "While AQP1 was downregulated in the tumor samples, AQP3 was particularly overexpressed in low-grade invasive tumors." (PMID 37761834, 2023). "An alternative explanation focuses on AQP1’s role in changing the cell shape and volume as tumor cells navigate through confined spaces." (PMID 37762642, 2023). "This study investigated the relationship between AQP1, 3 and 5 expression and gender, age, primary tumor site, histological grading, and TNM stage." (PMID 37334171, 2023). "In conclusion, our data suggested that the expression levels of AQP1, AQP3 and AQP5 were associated with regional lymph node metastasis, histological grading, and tumor location of CRC, respectively." (PMID 37334171, 2023). "This supports previous work that demonstrated diminished tumor microvascular density upon inhibiting AQP1, either through RNA interference or genetic knockouts, in various animal models." (PMID 37762642, 2023). "Inhibition of AQP1 reduced tumor growth in tumor-producing MMTV-PyVT mice or a mouse model of melanoma." (PMID 36803413, 2023). "While much attention has been focused on the role of AQP1 in tumor cell migration and angiogenesis, the evidence concerning its role in tumor cell proliferation is less consistent." (PMID 37762642, 2023). "This makes AQP1 an intriguing but complex target for potential therapeutic interventions aimed at inhibiting tumor cell proliferation." (PMID 37762642, 2023). "A heterogeneous pattern of AQP1 expression within the same tissues was also observed, indicating variability in the levels and distributions of AQP1 protein within single tumor masses." (PMID 37760476, 2023). "The downregulation of AQP1 appeared to be closely linked to the expression of MUC5AC and the aggressive behavior of the tumor." (PMID 37904849, 2023). "A study was conducted for comparative abundance and distribution analysis of AQP1 in tumor and normal tissue of the prostate." (PMID 36672280, 2023). "Aquaporin-1 (AQP1) in facilitating cell migration and potentially contributing to tumor progression." (PMID 38057925, 2023). "Recent research has also started to focus on the role of AQP1 in the broader tumor microenvironment." (PMID 37762642, 2023).
tumor (continued). "In brain, lung, prostate and colon tumours, AQP1 with high expression participates in cell migration and tumour angiogenesis." (PMID 35178393, 2022). "In another study using various cancer cell lines transplanted into mice, tumor growth and progression were hampered in AQP1 KO mice, similar to prior reports." (PMID 35847914, 2022). "Studies revealed that AQP1 is expressed in peripheral vascular endothelial cells and is involved in tumor angiogenesis." (PMID 36532729, 2022). "Functions annotated as transporter and potassium channel activities emerge via AQP1 (Aquaporin 1), a water channel membrane protein that promotes tumor angiogenesis (new blood vessel formation) by allowing faster endothelial cell migration." (PMID 35456196, 2022). "Increased AQP1 mRNA and protein levels have been detected in tumor biopsies of epithelial gastric adenocarcinoma and correlated with poor prognoses." (PMID 35163313, 2022). "Secondly, it has been shown that AQP1 knockdown in breast adenoma mice models resulted in decreased tumor formation and microvascular density within the tumor as well as reduced lung metastasis." (PMID 35163313, 2022). "High levels of AQP1 expression in MPM tumor cells were found to predict an increase in the survival rate." (PMID 35741021, 2022). "Finally, upregulated AQP1 levels have been found in various vascularizing and metastasizing cancer types, including brain, breast, lung, and colorectal cancers, and are associated with a poor prognosis, especially in tumor stages with increased hypoxic conditions." (PMID 35163313, 2022). "In vitro, MPM AQP1 inhibition can reduce cell adhesion, migration, and tumor sphere formation in an extracellular component type and histological type-dependent manner." (PMID 35741021, 2022). "Especially, AQP1 furthers tumor cell migration and acts independently of other known adverse factors, such as NMYC or NCAM." (PMID 35328549, 2022). "We have found through research that the mRNA and protein expression levels of AQP1 in ccRCC were significantly lower than those in normal kidney tissues, and the mRNA expression level of AQP1 gradually decreased with the increase of tumor grade." (PMID 35245343, 2022). "This “osmotic engine model”36 provides a perfect explanation on the mechanism of membranous AQP1-modulated tumor migration and angiogenesis." (PMID 33980862, 2021). "We demonstrate that migrating tumor cell express elevated AQP1 levels and a hypoxic biochemical phenotype." (PMID 33644043, 2021). "Our future investigation will focus on the role of AQP1-facilitated membrane permeability and plasticity and possible role in tumor cell thermogenesis for the migratory process." (PMID 34065626, 2021). "This is in congruence with the known data, and confirms that the tumor migration via AQP1 can be down-regulated by differentiation." (PMID 33467498, 2021). "AQP1 staining and hematoxylin counterstaining of the liver metastasis showed dissolution of the periportal structure in the tumor-infiltrated regions." (PMID 33671521, 2021). "The growth of xenografted tumor in mice is impaired by AQP1 knockout with reduced tumor angiogenesis and elevated necrosis." (PMID 33125833, 2021). "This positive correlation between AQP1 and β-catenin expression has already been documented in other tumor types and, in our opinion needs to be furtherly investigated in OC." (PMID 33807998, 2021). "Criteria for cell line selection were their AQP1 expression status, the expression of the established and clinically used markers for tumor aggressiveness and outcome NMYC and the expression neuronal crest adhesion marker (NCAM)." (PMID 33467498, 2021). "AQP1 expression was found positively correlated with β-catenin in serial paraffin-embedded sections of mice tumor tissues." (PMID 32814878, 2021).